NPY1R (neuropeptide Y receptor Y1)
Diseases named in the same sentence as NPY1R in open-access papers (continued):
Sharing a sentence is not in itself a finding about the gene and the disease.
oral cancers (1 paper, 2017). "In patients with oral cancer (n = 69), methylated NPY1R and NPY2R were independent prognostic factors for poor DFS, both individually and, even more so, in combination (odds ratio, 3.90; 95% CI, 1.523–9.991; P = 0.005)." (PMID 29100314, 2017). "When the NPY1R andNPY2R promoters were methylated in patients with oral cancers, the ratios were 2.39 (95% CI, 1.06–5.37; P = 0.036) and 2.93 (95% CI, 1.25–6.88; P = 0.014), respectively, and the hazard rate was 3.9 times higher (95% CI, 1.52–9.99; P = 0.005)." (PMID 29100314, 2017).
oropharyngeal cancers (1 paper, 2017). Carcinoma, predominantly squamous cell, arising from the epithelial cells of the oropharynx. "Our study associates NPY1R, NPY2R, and NPY4R methylation with tumor recurrence in oral and oropharyngeal cancers." (PMID 29100314, 2017). "The present study suggests that the methylation status of the NPY1R, NPY2R, and NPY4R genes is an independent indicator of DFS in patients with oral and/or oropharyngeal cancers." (PMID 29100314, 2017).
peripheral nerve injury (1 paper, 2023). Injury to a peripheral nerve. "Next, we analyzed the functional significance of Grp/Npy1r, Npff/Npy1r, and Cck/Npy1r INs to neuropathic pain using a mouse model of peripheral nerve injury." (PMID 37824208, 2023).
schizophrenia (1 paper, 2017). A major psychotic disorder characterized by abnormalities in the perception or expression of reality. "Genes with consistently lower expression levels in both medial rectus and schizophrenia tissues included NPY1R, TIMP2, and possibly NTRK2." (PMID 29302405, 2017). "Comparing baseline levels between muscle types, three schizophrenia-related genes (NPY1R, NTRK2, TIMP2) had lower levels of expression in medial rectus muscles." (PMID 29302405, 2017). "When gene expression by PCR arrays was analyzed exclusively in the medial rectus samples, we found that three schizophrenia-related genes were significantly altered: NPY1R, NRG1, and NTRK2 (adjusted p ≤ 0.012500)." (PMID 29302405, 2017).
social anxiety disorders (1 paper, 2020). "Taken together, our work highlights the potential of regulating NPY1R in social anxiety disorders and the alterations induced in brain circuitry as a consequence of early life stress and adversity." (PMID 32492699, 2020).
tumor (21 papers, 2012 to 2025). "Mechanistically, NPY activated ERK and Smad2 via NPY1R, synergising with TGFβ signalling in tumour cells expressing TβRI." (PMID 41298817, 2025). "Both Npy and Npy1r expression was retained in KPR172HC primary tumor and matched liver metastases, suggesting that it is maintained during metastatic spread." (PMID 40073121, 2025). "These genes are ANKRD6, ITIH3, SORCS3, NPY1R and CCDC178, which form a signature associated to adverse clinic-pathological features such as advanced tumor stage, poor prognosis and disease recurrence in GC." (PMID 38480611, 2024). "Among tumor samples, the LumA subtype had significantly higher NPY1R expression than all other BC subtypes." (PMID 35121782, 2022). "Since NPY1R is expressed in various types of tumors, the role of NPY1R, as a tumor-facilitated gene, has been postulated." (PMID 34620162, 2021). "Remarkably, we found that the mode of therapy, HPV status, smoking status, alcohol intake, tumor stage, and gene methylation status all indicated the likelihood of recurrence in patients with methylated NPY1R and NPY2R promoters." (PMID 29100314, 2017). "NPY1R upregulation also indicated better OS (HR = 0.39, P = 0.002) of advanced-stage patients and better OS (HR = 0.51, P = 0.032) of patients with Grade 3 tumor." (PMID 33878734, 2021). "NPY1R, an estrogen‐responsive gene, is high-expressed in BRCA patients and mediates the inhibitory action to tumor cells." (PMID 39119106, 2024). "Here, we identify that NPY and its receptor, Npy1r, are up-regulated in the highly metastatic genetically engineered KPR172HC mouse model of PC and demonstrate that both ligand and receptor are expressed in the primary tumor as well as liver metastases." (PMID 40073121, 2025). "NPY1R did not colocalize more with hypoxic tumor regions across cancer stages, but NPY5R significantly colocalized with hypoxia in stage T3 tumors by 6.53-fold relative to normal breast tissue." (PMID 37264315, 2023). "We investigated whether such analogs could antagonize NPY1R and NPY5R to influence cancer hallmarks in two different breast cancer cell lines while considering the effects of hypoxia, a major component of the tumor microenvironment." (PMID 37264315, 2023). "NMU was highly expressed in both tumor tissue and normal tissue, and NPY1R and SSTR5 were not collected in the HPA database." (PMID 33169793, 2020). "Among them, the expression of CNR2, GIP, GNGT1, NPY1R, SSTR5, and LEP in tumor tissue was significantly lower than in normal tissue, while the expression of GPSM2, and NMU was significantly highly expressed in tumor tissue." (PMID 33169793, 2020). "NPY1R was found to participate in the inhibition of cell proliferation via inactivating mitogen-activated protein kinase signal pathway in HCC cells and play an inhibitory role in tumor growth." (PMID 29423105, 2018). "Additionally, in multivariate analysis, after adjusting for baseline Ki67 levels, tumor stage, and treatment duration, CXCL9 (OR: 0.64, 95% CI: 0.41–0.89, p = 0.030) and NPY1R (OR: 1.52, 95% CI: 1.09–3.01, p = 0.047) remained significant independent predictors of Ki67 reduction." (PMID 40205245, 2025).
cancer (13 papers, 2012 to 2025). A tumor composed of atypical neoplastic, often pleomorphic cells that invade other tissues. "Npy and Npy1r were predominantly colocalized in cancer cells in both the KPfloxC and KPR172HC primary tumors." (PMID 40073121, 2025). "Pancreas-specific and systemic knockout of NPY1R significantly reduced liver metastasis in PC mouse models, while treatment with the NPY1R antagonist BIBO3304 markedly impaired cancer cell migration on cell-derived matrices." (PMID 41163091, 2025). "This study identified PSCA as a risk gene (hazard ratio > 1) for BRCA, while FREM1, NPY1R, CCL19 and CLIC6 were the protective genes for the cancer (hazard ratio < 1)." (PMID 39119106, 2024). "When cancer specimens were grouped by receptor status (ER + or TNBC), the high NPY1R group still displayed lower progression-free survival in both cancer subtypes compared to the low NPY1R group." (PMID 37264315, 2023). "Because of the high NPY1R expression in BC, it has been explored as a promising probe in cancer diagnosis." (PMID 35121782, 2022). "NPY1R expression was higher in BC compared to other 16 cancers across the TCGA cancer cohort obtained from HPA." (PMID 35121782, 2022). "The active role of THBS4 in regulation of cell motility and proliferation was further supported by the downregulation of NPY1R, which was shown to inhibit cancer cell proliferation, migration and invasiveness." (PMID 34631719, 2021). "Compared with the 60 normal control individuals, NPY1R was highly expressed in the cancer patients (P<0.01)." (PMID 25624911, 2015). "The Digital Gene Expression Displayer tool of the Cancer Genome Anatomy Project was used to identify the marker gene NPY1R, which is able to detect circulating cancer cells." (PMID 25624911, 2015). "Using primary KPR172HC cancer cells, we tracked cancer cell movement on CDMs upon pharmacological NPY1R inhibition using the NPY1R antagonist BIBO3304 to assess how inhibiting the NPY signaling axis might affect PC cell motility." (PMID 40073121, 2025). "This revealed that genetic Npy1r ablation did not significantly alter the abundance of stromal cell populations or ECM including cancer-associated fibroblasts [αSMA (ACTA2) and PDGFRB; fig." (PMID 40073121, 2025). "The observed reduction in the motility of KPR172HC cells upon BIBO3304 treatment suggests a role for NPY in cancer cell movement and could represent one of the modes through which NPY1R inhibition decreases metastasis to the liver." (PMID 40073121, 2025). "Furthermore, to assess non–cancer cell–autonomous contributions of NPY signaling through NPY1R, we crossed the KPR172HC model with Npy1r−/− whole-body knockout mice." (PMID 40073121, 2025). "We also investigated the cancer cell–intrinsic features of NPY1R inhibition in KPR172HC cells and found that their three-dimensional motility was decreased upon NPY1R inhibition when migrating upon CDMs." (PMID 40073121, 2025). "On average, 4.9-fold down-regulation of neuropeptide Y receptor Y1 (NPY1R) was observed, which has been shown to inhibit the proliferation, migration and invasiveness of cancer cells." (PMID 34631719, 2021). "Mice were subjected to daily intraperitoneal injections with BIBO3304 (1 mg/kg) or vehicle before and after intrasplenic injection, resulting in pharmacological NPY1R inhibition being present during the transit and liver colonization phase of KPR172HC cancer cell metastasis." (PMID 40073121, 2025). "Total NPY1R protein did not significantly change between normal and cancer tissue, however both NPY5R and CAIX protein were higher in stages 2–4 relative to normal tissue with significant 6-fold increases in stage T2." (PMID 37264315, 2023).
cancer (continued). "Therefore, our results suggest that NPY1R may not be a good probe for cancer diagnostics, but rather to predict endocrine sensitivity and treatment response." (PMID 35121782, 2022). "Epigenetic alterations have never been described in NPY1R and PPYR1 in any type of human cancer thus far." (PMID 30510283, 2018).
inflammation (2 papers, 2021 to 2024). Aberrant reaction of the microcirculation characterized by movement of fluid and leukocytes from the blood into extravascular tissues. "A correlation between NPY1R and intestinal inflammation had previously been made, and NPY1R signaling was speculated to be a potential therapeutic target for colonic inflammation." (PMID 34419055, 2021). "In the ovalbumin mouse model of airway inflammation, these neurons undergo significant reprogramming characterized by the upregulation of the NPY receptor Npy1r." (PMID 39345572, 2024).
neurodegenerative disease (1 paper, 2024). A disorder of the central nervous system characterized by gradual and progressive loss of neural tissue and neurologic function. "These strategies are anticipated to harness the neurogenic and cognitive potential of pharmacological interventions targeting the NPY1R and Ketamine pathways, offering significant promise for enhancing patient outcomes in neurodegenerative disease contexts." (PMID 38667284, 2024). "The inclusion of these models will allow us to directly assess the therapeutic improvements offered by the NPY1R agonist and ketamine combination in a context that closely mirrors the pathological state of neurodegenerative diseases, thereby enhancing the translational value of our findings." (PMID 38667284, 2024).
NPY1R also shares sentences with these, for which no sentence is quoted: depression (2 papers); mental disorder (2); adrenal tumor (1); airway hyperresponsiveness (1); binge eating disorder (1); Ewing sarcoma (1); Glucose intolerance (1); Hypertension (1); laryngeal carcinoma (1); malnutrition (1); metabolic disease (1); metastatic diseases (1); migraine (1); oral cavity cancer (1); ovarian carcinoma (1); renal cell cancer (1); uveal melanoma (1).